CD4 (CD4 molecule)
Diseases named in the same sentence as CD4 in open-access papers (continued):
Sharing a sentence is not in itself a finding about the gene and the disease.
infection (continued). "Further, recent infection testing algorithms using a multiple incidence assays in combination with additional clinical (e.g., CD4 cell count, RNA testing), laboratory (e.g., ART testing), and historical information should be explored for improving the accuracy of assay-derived incidence estimates." (PMID 21408182, 2011). "CD4+ T helper type 1 (Th1) cells secreting IFN-γ play critical roles in the clearance of infection." (PMID 21573182, 2011). "Blockade of type I IFN receptor at day 4 also modulated the CD4+ T response after WNV-NY infection." (PMID 22144897, 2011). "However, if early CD4+ T cell depletion leads to impaired immunity, then we would expect CD4 depletion in the chronic phase of infection to be higher than predicted by this theoretical relationship." (PMID 21359149, 2011). "Infection of activated CD4+ PBMCs with WT or V38E virus showed robust replication by both viruses." (PMID 21255440, 2011). "However, after these periods of CD4+ cell unresponsiveness, a huge CD4+ cell response was observed, reaching its maximum on day 30 of infection." (PMID 21814579, 2011). "However, the mNDK virus more efficiently infects CD4-positive cells than CD4-negative cells, suggesting that the mNDK virus induces CD4-independent and -dependent infections in CD4-negative and -positive cells, respectively." (PMID 21541353, 2011). "Even if the CD4-dependent HIV-1 particles are internalized into endosomes for productive infection, the CD4-dependent HIV-1 entry might occur before HIV-1 particle-bearing endosomes become acidic in late endosomes." (PMID 21541353, 2011). "This difference in disease progression could be due to clade D viruses switching from R5 to X4 phenotype earlier in infection, at higher CD4+ cell counts, than clade A isolates." (PMID 21655330, 2011). "In other words, the CD4 count or pVL at baseline is the result of dynamics over an unknown period of time, starting from an unknown value upon infection." (PMID 21701595, 2011). "Although Ag85B peptide 25-specific responsesreached an earlier peak and decreased earlier than did those of endogenouspolyclonal CD4+ T cell responses, the results with the two cellpopulations were similar, with endogenous CD4+ effector T cellresponses also diminishing by day 42 post-infection." (PMID 21637811, 2011). "Indeed, MyD88 deficiency resulted in complete abrogation of IFNγ production by CD4+ T-cells and an inability to control infection." (PMID 21253574, 2011). "However, the level of central memory CD4+ T cell destruction was essentially identical in early infection, indicating that target cell availability of ability to infect/destroy these cells was not likely a factor in early infection or the outcome." (PMID 21464951, 2011). "Thus while infection in activated CD4+ T cells is productive and cytopathic, in naïve T cells HIV-1 is present in latent state." (PMID 21994776, 2011). "After controlling for the confounding factors of age (and thus age related biological processes) we demonstrated that Treg as percentages of total CD4+ T cells were correlated with infection intensity, being significantly positive in the younger age group where infection was rising and peaking." (PMID 21347311, 2011). "This infection is particularly suitable for our study because SHIV89.6P infects both naïve and memory CD4+ T cells, and the loss of CD4+ T cells measured in blood can be taken to approximately represent the overall loss of CD4+ T cells in all anatomical compartments." (PMID 21359149, 2011). "Similarly, CA-074Me treatment of TE671 cells at 50 μM induced a 5-fold enhancement of the CD4-independent infection." (PMID 21541353, 2011). "Furthermore, phenotyping SIV infected cells in situ demonstrated marked and selective infection of CD69+ T cells in tissues, which is also consistent with direct infection of CD4+ T cells." (PMID 22096538, 2011).
infection (continued). "Finally, the infection of immature lymphocytes cannot be excluded since high levels of RNA were found in the thymus, possibly explaining the severe depletion in the CD4+ cell population." (PMID 22312347, 2011). "One, ES CD4+T cells contain a restrictive factor that limits infection." (PMID 21383972, 2011). "It is striking that DC-SIGN increases the relative rate of infection with the parental IIIB strain so that it resembles that of IIIBx indicating that the increased stability of the DC-SIGN:Env:CD4 complex may lead to more rapid co-receptor engagement." (PMID 22163292, 2011). "By contrast, T-cell receptor (TCR) transgenic or polyclonal CD4 T cells that had responded to immunization with cognate antigens or infection proliferate at <1% to 2.5% per day when examined after the initial expansion and contraction phases have been completed." (PMID 22022231, 2011). "The infection of CD4+ T cells accounts for many aspects of the viral pathogenesis, even if the capacity of lentiviruses to infect macrophages and other antigen-presenting cells (APC) plays a determinant role in the establishment, spreading and persistence of the infection." (PMID 21886773, 2011). "Among those patients who started HAART within the first 120 days of HIV infection, only three (7%) presented with HIV progression (one C event, one B event and one CD4 cell count decrease to < 350 cells/mm3 despite HAART initiation) within the first year of infection." (PMID 21831310, 2011). "Furthermore, it has also been demonstrated that mice with a genetic or acquired deficiency in CD4+ T lymphocytes display protracted WNV infection in the CNS, leading to uniform lethality by 50 days after infection." (PMID 21994755, 2011). "We hypothesised that HIV-1-infected thymic DC facilitate infection of thymocytes with R5 virus following cell-to-cell contact in a similar fashion to how blood pDC and mDC facilitate infection of CD4+ T cells isolated from blood." (PMID 21639903, 2011). "Because cathepsin proteases are activated by low pH in acidic late endosomes, the CD4-independent mNDK infection might occur through endosomes." (PMID 21541353, 2011). "CCR5 expression on CD4 cells on the other hand was relatively low in both infections." (PMID 21255440, 2011). "During infection drastic reduction of CD4+, CD8+ and CD19 + cell was noticed." (PMID 21612593, 2011). "The HIV-1 particles could be degraded predominantly by cathepsin B after the viral particles are internalized into endosomes, reducing the CD4-independent infection." (PMID 21541353, 2011). "The identification of a distinct population of airway memory CD4+ T cells present during the first two days of secondary infection allowed us to determine whether this population was reactivated by infection." (PMID 21647373, 2011). "They concluded that intravaginal vaccination with the live-attenuated strain L2 is safe, induces a systemic antibody and a CD4+ Th1-based immune response, but its protective efficacy is limited to reducing chlamydial burden at early time periods after-infection." (PMID 21747646, 2011). "DC-SIGN binding to HIV may also enhance DC infection directly and so contribute to the second longer-term mechanism of DC-mediated infection that involves transfer of progeny virus to CD4+ T cells." (PMID 22163292, 2011). "The results revealed that the pDCs were more prone to apoptosis after infection, which may be due to their high expressions of CD4 and CCR5." (PMID 22174949, 2011). "Interestingly, acute infection with T. cruzi in mice showed a large increase of CD4+/CD8+ DP T cells in their subcutaneous lymph nodes." (PMID 21886854, 2011). "Infection of these mice with HIV-1 leads to chronic viremia and subsequent CD4 helper T cell loss." (PMID 21695116, 2011). "To test this hypothesis we depleted CD4+ T cells using a specific monoclonal antibody (mAb) prior to and after i.n. infection of WT and IL-13−/− mice." (PMID 21573182, 2011).
infection (continued). "Moreover, α4β7 is closely associated with CD4 on a subset of CD4+ T cells that express high levels of CCR5 and are highly susceptible to infection." (PMID 21284901, 2011). "To test this hypothesis, we transferred highly pure sorted CD4+CD25+ T cells from P. chabaudi-infected mice four days after infection into MOG35-55 immunized mice, avoiding the introduction of parasites into the system." (PMID 21464982, 2011). "An early and lasting effect of infection is the downregulation of CD4 from the host cell surface." (PMID 20442859, 2010). "Recently we demonstrated that pre-patent schistosome infection and infections with either male or female worms alone that preclude the possibility of egg production, also induce type 2 responses, characterized by induction of CD4+ T cells and basophils that produce IL-4 in response to worm antigens." (PMID 21078176, 2010). "Infection studies with Vpr- or Nef-deleted viruses revealed that these two viral genes are not contributing to the mechanism of DCIR induction that is seen following acute infection of CD4+ T cells with HIV-1." (PMID 21085612, 2010). "These early studies suggested that HIV-1 could take advantage of the partnership between CD4 T cells and DCs, providing a microenvironment harboring infectious HIV-1 while at the same time increasing T cell susceptibility to infection." (PMID 21994702, 2010). "The concern of unknown time from infection could be lessened, at least partially, by grouping cohorts, which was largely driven by the CD4-based inclusion criteria." (PMID 20405044, 2010). "CD4+ T cells in the early phase of the infection were more frequent in the LGT than in the UGT." (PMID 21079691, 2010). "Infection of macrophages by primary R5X4 and X4 isolates of HIV-1 is inhibited by IL-4 and IL-13, an effect that is associated with down-regulation of surface CXCR4, CCR5 and CD4 expression." (PMID 20380696, 2010). "The concentration of CD4+ T cells harvested from the blood and lymph node tissue of infected patients correlates with infection and the ratio of [CCR5]∶[CD4]; infection will correlate more to CD4 expression when CCR5 is expressed in limiting amounts and vice versa." (PMID 20657663, 2010). "NK cells and CD4 T cells are essential within the first two weeks of infection." (PMID 20300179, 2010). "4-1BB ligation did not induce production of IL-4, a Th2 cytokine, IL-17, a cytokine which contribute to protection to MTB challenge and XCL-1, a chemokine released by suppressor CD8+ T cells during the chronic stage of infection with MTB that negatively affects production of IFN-γ by CD4+ T cells." (PMID 20544034, 2010). "Also, the percentage of CD4+CD3+ lymphocytes in the intestine was significantly higher in alcohol-consuming macaques before infection." (PMID 23584062, 2010). "Indeed, the CCR5Δ32 genotype has been associated with a restricted infection of MDM and CD4+ T cells by HIV-1 strains that use the CCR5 co-receptor (R5 HIV-1)." (PMID 20374633, 2010). "Delaying treatment by 48 hours caused the selective expansion of conventional CD4+ T cells rather than Treg cells, presumably due to infection-induced expression of high affinity IL-2 receptor by the former cell population." (PMID 21170302, 2010). "In addition, ZEBOV infection of human PBMC in vitro has been shown to induce apoptosis of CD4 and CD8 T lymphocytes." (PMID 20957152, 2010). "We suggest that HIV and other retroviruses could be exploiting this exosome antigen dissemination pathway intrinsic to mDCs, allowing the final trans-infection of CD4+ T cells." (PMID 20360840, 2010). "In contrast, V5 length decreased with increasing time after infection (β = −0.07, p<0.001), was decreased in stage 4 (β = −0.69, p = 0.01 compared to stage 1), and was decreased in those with CD4 counts below 200 cells/ml (β = −0.66, p = 0.002) compared to those with CD4 counts above 500 cells/ml." (PMID 21187897, 2010).
infection (continued). "FoxP3, a marker of Treg activity, increases in CD4+CD25+ T cells following FIV infection." (PMID 20507636, 2010). "Interestingly, for FliC431–439-specific CD4+ cells identified in this manner, ∼10% were Foxp3+ in F1 mice prior to and at each time point after infection." (PMID 20714351, 2010). "Using a modeling approach to investigate the dynamics of virus and CD4+ T cells, we find that the kinetics of viral load and the loss of CD4+ T cells to infection are not consistent with a cytolytic mechanism of CD8+ T cells killing SHIV infected cells." (PMID 21152101, 2010). "The enriched CD4+ T cells in the interface of density medium and plasma yielded approximately 98% purity; subsequently stimulated with phytohemagglutinin (0.5 ug/ml) and interleukin-2 (10-20 U/ml) before infection with virus stocks." (PMID 20064199, 2010). "Conversely, innate responses can also have detrimental effects at all stages of infection, promoting virus transmission and the establishment of infection, enhancing subsequent virus replication and spread and contributing to CD4+ T cell destruction and disease progression." (PMID 20937128, 2010). "The infection was of minimal influence on counts of splenic CD4 CD8 T lymphocytes and γδ T-lymphocytes although a reduced ability of splenic lymphocytes to respond to non-specific mitogens indicated general immunosuppression in mice infected with SPI-2 positive S. Enteritidis mutants." (PMID 20226037, 2010). "Among CD4+ T cells, IL-17A-producing cells reached the peak on day 6 post-infection (A2)." (PMID 20585449, 2010). "Upon infection, antigen-specific CD4+ T cells can be as many as 1 in 20 in the spleen, and antigen-specific CD8+ T cells may be one in two." (PMID 20222966, 2010). "Moreover, mucosal HIV-1 gp41-specific IgA derived from highly exposed seronegative individuals was able to block HIV-1 epithelial transcytosis and neutralized CD4+ cell infection." (PMID 21994611, 2010). "HIV Jurkat-Raji/CD4 coculture infection displays a high resistance to neutralizing mAbs (25–50 μg/ml for 80–95% inhibition in kinetics experiments versus 5–10 μg/ml for cell-free infection (DM, DD unpublished observations), another indication of cell mediated virus transfer." (PMID 20195464, 2010). "The immunological benefit of preventing CD4+ T cell depletion in LN and mucosal tissues is obvious, as for acute infections: the mucosa is the dominant site of infection, and the gastrointestinal tract/other mucosal tissues contain at least half of the body's T cells." (PMID 20485497, 2010). "We studied the effects of infection on viral target cells (CD4+ T cells or CD68+ macrophages) in tissue through immuno-histochemistry (IHC), to precisely define the most effective and the ultimate treatment start time able to reduce viral dissemination in this model." (PMID 20485497, 2010). "To evaluate if the lower percentage of infected cells over time could result from the loss of CD4 expression at the cell surface, we monitored the CD4 positive cells during 7 days of infection with HIV-1NL4-3." (PMID 20174665, 2010). "CD4+ T helper 1 (Th1) cells are critical for host protection against infection, but may also contribute to immunopathology." (PMID 21079691, 2010). "Because IL-7 can increase the survival of T cells, we tested whether CD4+ T cells in HIS mice would be rescued by IL-7 following infection by HIV." (PMID 20700454, 2010). "Both IFN-γ and TNF-α can be produced after T. cruzi-induced triggering of the innate immune response (mainly by NK/NKT cells and macrophages/DC respectively), as well as by CD8+ and CD4+ T lymphocytes later in the infection course, as part of the acquired response to the parasite." (PMID 20442858, 2010). "We hypothesize that HIV-1 could be exploiting this preexisting cellular pathway of antigen uptake and retention inherent to mDCs, favoring and enhancing viral trans-infection of CD4+ T cells." (PMID 20360840, 2010).
infection (continued). "In a primary infection, the migration of T helper cells to the large intestine is critically required for the expulsion of T. muris but colonic CD4+ cell accumulation can be demonstrated in both resistant and susceptible strains." (PMID 19968992, 2010). "Infiltration of immune cells, especially CD4+ T cells, was dramatically increased in p38αfl/fl mice two weeks after infection, consistent with previous reports that CD4+ T cells infiltrate into the colonic mucosa and play a central role in the clearance of this bacterium." (PMID 20532209, 2010). "However, while the percentage of IFN-γ producing CD4 T cells increased 10 days after infection in wild-type mice, the increase of IFN-γ producing cells was considerably less in MyD88-deficient mice." (PMID 20668698, 2010). "In our studies, levels of downregulation of Nef-mediated CXCR4 derived from unintegrated DNA correlated well with results obtained in productive infection and are also in agreement with the finding that such downregulation occurs to a lesser extent than is seen for CD4." (PMID 20465832, 2010). "Similarly, there is an accumulation of CD4+ cells in the gut following a challenge infection in both ES/IFA-vaccinated and PBS/IFA-injected control mice." (PMID 19968992, 2010). "After parasite inoculation, most mouse strains, including C57BL/6 mice, are resistant to infection and develop a protective CD4+ Th1 immune response, while a few strains such as BALB/c mice are susceptible to infection and develop a CD4+ Th2 type of immune response." (PMID 20140197, 2010). "In the initial weeks post-infection, the great majority of dying cells are uninfected CD4+ T cells." (PMID 20617170, 2010). "An understanding of the CD4+ T cell responses induced by schistosome worms during pre-patent infection is therefore a prerequisite to elucidating how these parasites evade immune injury and establish productive infections." (PMID 21078176, 2010). "However, the pDC counts were positively correlated with the CD4+ T-cell counts (r = 0.479, P = 0.018) during the chronic phase of infection (76 to 819 p.i), as previously reported." (PMID 21118577, 2010). "Thus, peripheral blood derived CD4 T cells from HIV+ subjects in the acute stage of infection depleted of autologous Treg cells proliferated more efficiently and secreted more IFN-gamma when stimulated with HIV antigens." (PMID 20174666, 2010). "In addition, CD4+ lymphocytes from the LTNP subset displaying anti-CCR5 Abs were found to be resistant to in vitro infection with R5-tropic HIV-1 strains." (PMID 21994649, 2010). "Virus was cleared despite profound CD4 T cell depletion and aberrant CD8 T cell activation but this may have increased susceptibility to a fatal secondary infection." (PMID 20540811, 2010). "Therefore, by comparing these two groups, we can control for the rate of CD4+ T-cell decline, progression rate, and duration of infection." (PMID 20523897, 2010). "Flow cytometry data gated on CD4+Thy1.2+ CFSEneg divided B5 Tg cells were collected at several time-points during the infection, and subjected to boolean gating analysis, which distributed them into the 32 possible subsets generated by testing every possible combination of the 5 activation markers." (PMID 21124875, 2010). "The reason for this apparent discrepancy is not clear and could be due to the different strain of parasite used for infection or to the method employed for CD4+ T cell re-stimulation in vitro." (PMID 20442858, 2010). "Many features are shared by non-pathogenic natural host and pathogenic non-natural host infection including sustained high level viremia, vigorous immune activation during acute infection, and extensive depletion of gut mucosal CD4+ T cells." (PMID 20865163, 2010). "Infection of NP2/CD4/CXCR4 cells is 35X (MCN) and 160X (MCR) greater than on HeLa/CD4 cells." (PMID 20929586, 2010).